NRP1 (neuropilin 1)
Diseases named in the same sentence as NRP1 in open-access papers (continued):
Sharing a sentence is not in itself a finding about the gene and the disease.
tumor (continued). "Reduced Nrp1 expression in LN229 GBM xenografts, however, leads to increased intratumoral angiogenesis and vascular permeability, suggesting additional functions for tumor cell-expressed Nrp1 in cross-talk with stromal components in the GBM microenvironment." (PMID 28938007, 2017). "Moreover, an important role of the NCD in this pathway agrees with prior observations that the NCD enhances complex formation of NRP1 and VEGFR2 in VEGF165-stimulated ECs and promotes ABL1 function in tumor cells." (PMID 28289053, 2017). "Additionally, numerous transcriptional regulators act downstream of NRP-1 such as SNAI117, a transcriptional repressor pivotal for cell differentiation and survival that reverses the tumor suppressive effects induced by TGFβ1 in early stage breast cancer." (PMID 28607365, 2017). "Considering the important role of Nrp1 in MaSCs, we examined its impact in MMTV-Wnt1 tumor growth." (PMID 28887477, 2017). "NRP-1, on forming a complex with plexins also interacts with the secreted class 3 semaphorins (SEMA3 A,B,C,D,F) that are antagonistic to VEGF signaling, hence promoting tumor apoptosis and inhibiting cell migration." (PMID 28607365, 2017). "It is also reported that inhibiting NRP1 using monoclonal antibodies could inhibit the formation of integrin α5β1-NRP1 complex, the activation of FAK pathway and the adhesion of tumor cells to fibronectin." (PMID 27863391, 2016). "It has been reported that NRP1 can control EGFR signaling and tumor growth." (PMID 27881077, 2016). "The rats were delivered with shRNA-minicircle DNA vector targeted against NRP-1 using UTMD 28 days after tumor implantation, a validated non-invasive technique for gene delivery." (PMID 27542226, 2016). "We then investigated whether pharmacologic inhibition of Nrp1 in wild-type mice with EG00229, which blocks the b1 domain of Nrp1, would have similar effects on tumor growth." (PMID 26755653, 2016). "Therefore, we used a neutralizing anti-Nrp-1 Ab18 to treat IL10−/− and WT tumor-bearing mice on days +9 and +12 after B16/F10 implantation." (PMID 27075020, 2016). "F4/80 GAMs in tumor tissue of wt mice stained positive for Nrp1 expression, while Nrp1 was not detectable in GAMs of Nrp1MgKO mice." (PMID 26755653, 2016). "The NRP1 cytoplasmic domain has also been reported to interact with the non-receptor tyrosine kinase ABL1 in tumour cells." (PMID 26923176, 2016). "NRP-1 has been identified as a co-receptor for multiple growth factors, including VEGF-A, FGF, HGF and others, and is expressed on both endothelial and tumor cells." (PMID 27542226, 2016). "Another group reported that NRP1 augments the FN fibril assembly activity of integrin α5β1 by interacting with GIPC1 and c-Abl using its SEA motif and activates tumor microenvironment.These results provided evidence that NRP1 regulates cell adhesion dependent on integrin α5β1 function." (PMID 27863391, 2016). "Furthermore, our data suggest that Nrp-1-derived Tregs appear to be quite different from CD4+Nrp1+ T cells and that these cells most likely play different roles in anti-tumor responses." (PMID 27075020, 2016). "In addition, the anti-VEGF-A monoclonal antibody bevacizumab targeting tumor vascularization has a transient inhibition on GBM tumor growth, but the effect is greatly attenuated in the GSC population due to the VEGFR2-Neuropilin-1 autocrine loop." (PMID 26510911, 2015). "In light of the fact that the NRP1 receptor does not have intrinsic kinase activity, the function of NRP1 in tumour cells requires more detailed analysis of the signal transduction pathways." (PMID 26147006, 2015). "Neuropilin 1 was shown to serve as a co-receptor for VEGF, and NRP1 forms complexes with VEGFR2 to enhance the binding of VEGF to VEGFR2 and promotes VEGF165-mediated tumour angiogenesis, cell migration and tumourigenicity." (PMID 26147006, 2015). "As in EC-NRP1-KO tumours, pericyte coverage of tumour vasculature was not affected by an NRP1 cytoplasmic deletion." (PMID 26159543, 2015).
tumor (continued). "Equally, reductions in β3-integrin expression without concomitant changes in NRP1 do not drastically alter tumour angiogenesis (particularly in already-established tumours)." (PMID 26159543, 2015). "Further, tumor vascular density is decreased when anti-NRP1B is combined with murine anti-VEGF, which may, therefore, make NRP1 a potential target for improving the efficacy of anti-VEGF therapy." (PMID 25954957, 2015). "NRP-1 is also expressed by various stromal cells, including fibroblasts, endothelial and immune cells, which can be activated by growth factors different from VEGF-A and contribute to tumor progression." (PMID 26090340, 2015). "As a coreceptor of TβRI/TβRII, NRP1 can curb tumor apoptosis and accelerate tumor growth via both canonical and non-canonical signaling." (PMID 24736504, 2014). "We found that NRP-1 was highly expressed in tumor specimens, compared with normal (non-cancerous) oral tissues." (PMID 24999732, 2014). "We speculate that after curative hepatectomy, peritumoral hepatocytes expressing abundant of NRP-1 or VEGFR-2 may play a positive role by providing an infertile soil for endothelial cells and primary tumor and subclinical metastatic tumor cells." (PMID 25333267, 2014). "These assays demonstrated that the abnormal expression of RANKL, HIF-1α, NRP-1 and VEGF proteins seen in clinical PCa tumor specimens could be easily detected in the isolated CTCs." (PMID 24551200, 2014). "In vivo, miR-338 also decreased tumor growth and suppressed D-MVA by targeting NRP1." (PMID 24736504, 2014). "Although Nrp1 expression on tolerant mouse T cells did not contribute to the dysfunction, it did provide a unique marker of tumor/self-reactive T cells displaying a tolerant phenotype." (PMID 25343644, 2014). "When tumor size was excluded as a determinant of outcome, high peritumoral NRP-1 or VEGFR-2 expression was still associated with markedly longer OS and TTR in patients with a maximum tumor diameter of 5 cm." (PMID 25333267, 2014). "Nevertheless, NRP1-mediated extracellular matrix remodeling takes place in primary arterial endothelial cells and tumor cells and appears to be mediated by the NRP1 cytoplasmic tail without requirement for VEGFR2 activation by VEGF." (PMID 24521511, 2014). "Using tumor recurrence at one year as the cutoff for early tumor recurrence, patients with high peritumoral NRP-1 expression had a markedly lower incidence of early recurrence (11.1%, 6/54 vs. low NRP-1 expression: 26.9%, 43/160, p = 0.017)." (PMID 25333267, 2014). "The iRGD achieved tumor homing by initially binding to integrin αvβ3 and then being proteolytically cleaved to CRGDK/R, which can penetrate into tumor cells and tissues by binding with neuropilin-1." (PMID 23977262, 2013). "The cell membrane and/or cytoplasm of most tumor cells in the NPC sections stained intensely with NRP-1 antibody, while negative immunostainings were observed in all non-cancerous nasopharyngeal tissues." (PMID 24053763, 2013). "For example, KDR expression by itself was not significantly altered between tumor and normal samples, but co-expression of KDR with VEGFC, NRP1, and PLXNC1 was associated with tumors." (PMID 23667446, 2013). "The analysis of Nrp-1 expression has indeed revealed that Nrp-1-negative bona fide pTreg cells were significantly enriched at tumor site compared to spleen, ranging around 40–90% of total tumor-infiltrating Treg depending on the tumor type." (PMID 23986759, 2013). "Thus, differences in expression of NRP1 and NRP2 measured by microarray can be assumed to be primarily due to endothelial cells, and differences in PLXNB1 due to tumor cells." (PMID 23667446, 2013). "We have clearly documented that the hypoxia-mediated HIF-1α-dependent up-regulation of NRP-1 not only confers the angiogenic properties on the HT1080 cells leading to vasculogenic mimicry, but also augments their tumour-forming ability, thereby acting as a double-edged sword in these cells." (PMID 23185562, 2012).
tumor (continued). "They reported that these peptides were cleaved on the membrane of tumor cells by a furin-like protease, and this exposed a CendR motif (RGDK/R) that could bind to Nrp1." (PMID 22948112, 2012). "We applied a monoclonal antibody that targets the VEGF binding site on NRP-1 without interfering with its semaphorin signalling, and which has been shown to reduce neovascularisation in tumour models." (PMID 22817681, 2012). "The HT/shNRP-1 cells failed to form tumours even after hypoxia-priming, once again underscoring the crucial role of NRP-1 in the tumour formation by the HT1080 cells." (PMID 23185562, 2012). "The hypoxia-primed MC3T3#24 cells neither showed any tubule formation on matrigel nor did their NRP-1 expression change after hypoxia-exposure (data not shown), suggesting that the effects of hypoxia were perhaps tumour cell-specific." (PMID 23185562, 2012). "Silencing of NRP-1 in the HT1080 cells completely abrogated the tumour growth, even after their priming with hypoxia, indicating that this is an excellent therapeutic target for containment of such tumours." (PMID 23185562, 2012). "In addition, when conditional NRP-1 knockout mice were crossed with VEGF transgenic mice, VEGF was unable to promote tumor growth, even though efficient tumor angiogenesis was still observed." (PMID 23125933, 2012). "Therefore, accurate estimates of neuropilin expression and the relative density of NRP1 compared to NRP2 are required, as the response to anti-VEGF therapy is sensitive to this property of the tumor microenvironment." (PMID 22104283, 2011). "We identified tumor cell-secreted platelet-derived growth factor-B (PDGF-B) as a crucial factor controlling the differentiation and recruitment processes through an interaction with neuropilin-1 (NRP-1) in mesenchymal stem cells." (PMID 20687910, 2010). "It has been proposed that NRP1 may store or sequester VEGF165 and attract endothelial cells towards tumor, contributing to angiogenesis via juxtacrine or paracrine mechanisms." (PMID 20085644, 2010). "The available binding site concentrations of the matrix components are independent of the NRP1 density in the tumor." (PMID 18713470, 2008). "In contrast, factors that regulate NRP-1 expression in ECs and tumour cells are not fully elucidated." (PMID 12618892, 2003). "The exact role of NRP-1 in tumour cells remains to be elucidated; however, it is possible that NRP-1 may augment tumour angiogenesis and/or tumour cell survival." (PMID 12618892, 2003). "NRP-1 could act as a coreceptor that enhances VEGF-165 function in both VEGFR-2- and NRP-1-positive tumour cells." (PMID 12618892, 2003). "Regarding integrins, few data are available in which a PROTAC targeting PD-1/PD-L1 was designed using the tumor-penetrating iRGD peptide, binding intαvβ3 and inducing neuropilin-1-mediated transcytosis for deep tumor penetration but not considering integrins as therapeutic targets." (PMID 41492134, 2026). "In addition, NRP-1 has an ability to increase VEGF receptor signaling and pro-angiogenic activity, which indicates increased intratumoral angiogenesis and disease progression, and it is found on both endothelial and tumor cells." (PMID 40430075, 2025). "Endothelial NRP1 positivity combined with limited vascular-astrocytic interaction and aberrant GFAP expression in SHH-MB may contribute to dysregulated angiogenesis and tumor progression." (PMID 40805120, 2025). "To further improve the DR5-B antitumor efficacy by engaging additional tumor targets, we have recently engineered a multitarget fusion protein SRH-DR5-B-iRGD, containing VEGFR2-specific peptide SRH at the N-end and integrin αvβ3/NRP1-specific peptide iRGD at the C-end of the DR5-B protein." (PMID 40841907, 2025).
tumor (continued). "Previous reports demonstrated some factors, such as Neuropilin-1 (NRP1) and enhancer of zeste homolog 2 (EZH2), restrictively deleted in Tregs impaired the transcription activity of FOXP3, restricting Treg-suppressive ability and conferring resistance to tumor growth in the host." (PMID 39446493, 2024). "Of note, cooperation between all three receptors and VEGF-A may also characterize malignant states, since NRP1, VEGFR2, ENG and VEGF-A are overexpressed in cancer;4,77–86 this was shown to be prominent in angiogenesis, which has a key role in tumor formation and development." (PMID 38242992, 2024). "PEI-elastase could be uptake by NRP1 negative tumor cells, suggesting that PEI-elastase avoided the restrictions of NRP1-mediated endocytosis and achieved NRP1 negative tumor cell-killing ability." (PMID 39068444, 2024). "Nevertheless, targeting NRP1 could be a potential approach to preventing SARS-CoV-2 entry and for developing potential anti-tumor drugs, with a peptide-based inhibition in anti-angiogenesis, anti-proliferation, and anti-migration of tumor cells." (PMID 38138098, 2023). "However, when NRP-1 is downregulated in TAMs, SEMA3A/PlexinA1/PlexinA4 stops TAMs from migrating and inhibits their immunosuppressive and angiogenic properties, which impedes tumour growth." (PMID 37685898, 2023). "The transmembrane receptor Nrp1 is a co-receptor for VEGF expressed on microglia that, when activated, drives microglia to migrate toward tumor areas and polarize toward the M2 phenotype, and correlates with tumor neovascularization and immunosuppressive microenvironment formation." (PMID 37700840, 2023). "To further establish clinical relevance of the Sema3A/NRP1 axis in GBM, we determined the expression levels of each of the signaling components in GBM specimens by tissue microarray (TMA), in which 68 GBM specimens and 10 non–tumor-bearing brain tissues were included." (PMID 37788099, 2023). "Previous studies have shown that NRP1 is widely expressed on the surface of vascular endothelial cells, acting as a coreceptor of VEGF, forming complexes with VEGF receptors (VEGFRs) to enhance the interaction between VEGFRs and VEGF, thus promoting tumor metastasis." (PMID 37701532, 2023). "In some experiments, we observed a delay in the onset of tumor growth with the NRP-1 KO cells, but this was not reproducible, so it may have been associated with different viability states of the cells at the time of engraftment." (PMID 37175499, 2023). "Another immunohistochemical study using 93 tumor samples showed that patients bearing tumors with moderate or high NRP1 levels had significantly shorter overall survival compared to patients with no detectable or low NRP1 expression." (PMID 37894289, 2023). "NRP-1 functions as a receptor on M2 macrophages, and a targeting strategy using AGuIX-KDKPPR nanoparticles could also be extended to other approaches, notably diagnostics, perfecting tumor detection, and monitoring therapeutic responses." (PMID 36986856, 2023). "Moreover, the vascular endothelium is the gateway to the tumor for imaging agents, but NRP-1 is expressed in all vessels, not just tumor vessels, resulting in weaker specificity for iRGE than for iRGD." (PMID 36199363, 2022). "NRP1 inhibition suppressed expression of the mesenchymal and stem cell markers ZEB1 and ITGA6, respectively, compromised spheroid-initiating capacity and exerted potent anti-tumor effects on claudin-low orthotopic xenografts (12.8-fold reduction in endpoint tumor volume)." (PMID 35078508, 2022). "In addition, the C-end Rule motif can be uncovered by proteolytic cleavage after tumor-homing, the uncovered R/KXXR/K motif can bind to neuropilin-1 (NRP1), and the NRP1 binding activates the endocytic bulk transport pathway and increases tumor tissue permeability." (PMID 35631583, 2022).
tumor (continued). "Likewise, the cell-penetrating peptide iRGD containing the CendR sequence can first target integrin receptor to cross the blood–brain barrier and then provides the second moiety to bind Neuropilin-1 (NRP-1) and Neuropilin-2 (NRP-2) for crossing the brain–tumor barrier." (PMID 36531004, 2022). "Notably, NRP1flflNRP2flfl.ECKO tumors also exhibited significantly less vasculature than either NRP1flfl.ECKO or NRP2flfl.ECKO tumors, suggesting that the dual targeting of both NRP1 and NRP2 elicits a compounded antiangiogenic response to inhibit tumor development and growth." (PMID 36970722, 2022). "Moreover, the mRNA expression of NRP1 was also evaluated, and no change was noted regardless of the treatment conditions or the tumor model (data not shown)." (PMID 36457009, 2022). "In recent years, targeting overexpressed receptors on tumor cells with radiolabeled peptides has become very important in anticancer therapy, so we decided to investigate two novel radioconjugates based on VEGF-A165/NRP-1 inhibitors: the A7R peptide and Lys(hArg)-Dab-Pro-Arg peptidomimetic." (PMID 35056995, 2022). "Galectin-1 may promote NRP-1 expression by activating IL-8 secretion, and then galectin-1 binds to NRP-1 that is highly expressed on the surface of CAFs or PSC, ultimately promoting PDAC tumor immune evasion." (PMID 36428567, 2022). "To determine whether cotargeting endothelial NRP1 and NRP2 impedes tumor growth in already established tumors, we next performed intervention CMT19T allograft studies in our NRP1flflNRP2flfl.ECKO animals, delaying tamoxifen administrations until 7 days after cell implantation." (PMID 36970722, 2022). "Additionally, it has to be mentioned that no statistical association was observed between the tumor grade/stage of disease and the VEGF, HB-EGF, PDGF-CC and NRP-1 serum levels." (PMID 35887839, 2022). "Similarly, a different study using a neuropilin-1-targeted MB showed identical tumor accumulation compared to non-targeted counterparts at 4 min p.i., with differences due to MB attachment only visible as late as 8 min post-injection." (PMID 34793563, 2021). "Similarly, tumor volume and weight were significantly reduced in sh-NONHSAT114552 group compared to that in control group, but this decrease was rescued in sh-NONHSAT114552+Lv-NRP1 group." (PMID 34721048, 2021). "NCL aptamer-siRNA (AS1411-siRNA) chimeras specific for SLUG (aptNCL-SLUGsiR) and NRP1 (aptNCL-NRP1siR) can be used for specific tumor invasion and angiogenesis suppression in only metastatic tumor cells without blocking the signaling pathways of cells that are under physiologic conditions." (PMID 34723284, 2021). "Moreover, tumor genes including c-Myc, KLF15, and NRP1 were reported to be targeted by miR-376a, which may explain why the re-expression of CTC1 cannot fully rescue the miR-376a overexpression-induced defects." (PMID 33937245, 2021). "Notably, non-immune CD45− cells (TU) from the MC38 tumor single cell suspension, including the cancer cells, hardly expressed NRP-1, suggesting that any intratumoral Nb1 effects are likely to be directed towards immune cells." (PMID 33266104, 2020). "Despite the lack of catalytic activity, NRP-1 is considered to be an independent mediator of tumor development and progression, since it is extensively overexpressed in many cancerous cells, which is associated with tumor progression, metastasis and poor clinical outcome." (PMID 33374715, 2020). "However, multivariable analyses identified independent favorable prognostic significance of expression of NRP1 only when specifically assessed in perivascular tumor cells and not for total tumor cell expression of NRP1." (PMID 31880322, 2020). "Treg-selective deletion of essential Treg factors such as Neuropilin-1 (Nrp-1), suppressor of cytokine signaling 1 (SOCS1), enhancer of zeste homolog 2 (EZH2), Eos (IKzf4), or CARMA1 leads to Foxp3 downregulation and inflammatory cytokine secretion, conferring resistance to tumor growth in the host." (PMID 33024109, 2020).